ADAM24P (ADAM metallopeptidase domain 24, pseudogene)
Synonyms: ADAM24
Gene: Unprocessed pseudogene on chromosome 8 (17,469,518 to 17,471,618, forward strand). Ensembl gene ENSG00000214607.
Diseases named in the same sentence as ADAM24P in open-access papers:
ADAM24P is named in the same sentence as 1 disease in open-access papers, as found by Europe PMC text mining. Sharing a sentence is not in itself a finding about the gene and the disease. The quoted sentences say what the papers report.
endometriosis (1 paper, 2020). The growth of functional endometrial tissue in anatomic sites outside the uterine body. "Of the previously reported variants associated with endometriosis, most had the directionally concordant effect except for rs1250241, chr2:g.216 295312 T > A at 2q35, FN1, rs517875, chr3:g.174350886 C > A at 3q13, RAP1BP2, and rs13271465, chr8:g.17282411 T > C at 8p22, MTMR7/ADAM24P." (PMID 31488892, 2020).